MMP7 (matrix metallopeptidase 7)
Diseases named in the same sentence as MMP7 in open-access papers (continued):
Sharing a sentence is not in itself a finding about the gene and the disease.
tumor (continued). "Members of MMPs family, including MMP7 play a distinct role in tumor cell metastasis via metrix degradation and integrin-mediated migration along with invasion are critical steps for the metastasis of tumor cells." (PMID 24143235, 2013). "Additionally, MMP7 has been shown to play a crucial role for the invasive and metastatic potential of tumor cells." (PMID 24325363, 2013). "It has been reported that overexpression of MMP-7 is associated with tumor proliferation and a poor prognosis in human non-SCLCs." (PMID 23300791, 2012). "For example, MMP7 could cleave Fas ligand, thereby lowering the impact of chemotherapy on the tumor by abrogating apoptosis." (PMID 21857934, 2011). "Activin A promotes tumor cell aggressiveness by increased expression of MMP-7 and N-cadherin." (PMID 22069487, 2011). "Several mechanisms have been proposed by which MMP7 promotes tumor growth." (PMID 21991341, 2011). "Interestingly, the strong expression of β2-AR and MMP-7 emerged at the same region of the tumor tissues, suggesting an intimate relationship between MMP-7 and β2-AR." (PMID 20939893, 2010). "Andrographolide may also inhibit angiogenesis for tumour metastasis via down-regulating matrix metalloproteinases-7 (MMP-7) expression, possibly by inactivating activator protein-1 (AP-1) through suppressing PI3K/Akt signalling pathway." (PMID 20465823, 2010). "Another study indicated that FGF-2 could directly upregulate MMP-7 gene expression in human tumor cell lines and umbilical vein endothelial cells through AP-1 and STAT3." (PMID 20939893, 2010). "MMP7 is widely expressed in human cancer and in tumor cell lines." (PMID 19266094, 2009). "This relationship between MMP7 and Fas activation could also have implications during tumor progression." (PMID 19266094, 2009). "During the generation of resistant cell lines, only few clones may survive each round of therapy, suggesting that inside the heterogeneous tumor cell population only cells with high expression of MMP7 survive." (PMID 19266094, 2009). "Furthermore, since MMP7 seems to promote tumor survival, it is interesting to note that oxaliplatin treatment also induces MMP7 expression both in normal as well as in resistant cells." (PMID 19266094, 2009). "Additionally, chemo-endocrine therapy can also effectively down-regulate MMP7, which in turn can influence tumor cell invasion and migration." (PMID 19785773, 2009). "Staining for MMP7 was observed in the cytoplasm of the tumor cells." (PMID 18992165, 2008). "Interestingly, a marked increase in expression was found for Il-8, HD-6 and MMP-7 expression in the tumours (8-, 22- and 70-fold, respectively)." (PMID 18212756, 2008). "All the tumor cases exhibited cytoplasmic overexpression of mmp-7." (PMID 18681964, 2008). "Essential differences with our study are, however, that the latter studies were carried out using immunohistochemistry, focusing on MMP-7-expressing carcinoma cells at the invasive front, whereas our ELISA antigen values were derived from representative overall parts of the tumours." (PMID 16538217, 2006). "MMP7 was the only marker that exhibited increased levels in tumours." (PMID 16755296, 2006). "Thus, examination for the presence of MMP-7 in tumour biopsy specimens before treatment is expected to be useful for decision making about the treatment course and to predict prognosis." (PMID 14647147, 2003). "MMP-7 plays important roles in tumour invasion and metastasis." (PMID 14647147, 2003). "Cases with tumour invasion of the SM had significantly more MMP-7 expression at the invasive front." (PMID 14647147, 2003). "MMP-7 is regulated by β-catenin expression and is a proteolytic enzyme related to tumour invasion." (PMID 11953860, 2002).
tumor (continued). "However, our work is the only one also assessing MMP-7 concentration in patients with benign lesions, which is an innovative element, and the result of the assessment of differences in concentrations between groups taking into account benign lesions provides new information." (PMID 41462922, 2025). "This may indicate that tumours in more advanced stages produce more MMP-7." (PMID 40565125, 2025). "Therefore, we have reanalysed the single‐cell data to focus specifically on MMP7+ tumour cells." (PMID 39187937, 2024). "Lastly, while we used multiplex immunofluorescence to validate the presence of CD14+APOE+ cells and MMP7+ tumour cells, additional validation using other complementary techniques such as flow cytometry or single‐cell RNA sequencing could provide a more robust confirmation of our findings." (PMID 39187937, 2024). "In addition, focusing on MMP7+ tumour cells could provide a more precise understanding of their specific interactions with immune cells." (PMID 39187937, 2024). "Azacitidine treatment of a primary UL culture decreases tumour cell viability (probably via hypomethylation/activation of tumour-suppressor genes), ECM production and the expression of genes encoding WISP1, c-MYC and MMP7 proteins, which are the targets of the WNT/β-catenin signalling pathway." (PMID 36982825, 2023). "Taking advantage of MMP7 deficient mouse models, the EMT-related transcription factors, including Snail, Slug, Twist, Smad4 and ZEB1, and the several ECM components, including Fibronectin, Collagen, Vimentin and N-cadherin, were reduced in tumor progression and fibrotic disease model." (PMID 35659367, 2022). "The implementation of EMT program by tumor cells and MMP7 synthesis share the Wnt/β‐catenin pathway, as proved by the simultaneous inhibition of the phenotype transformation and the inhibition of MMP7 direct production by hydroxysteroid sulfotransferase 2B1b (SULT2B1b) or Thymoquinone." (PMID 35789101, 2022). "MMP-3 and MMP-7 expression in tumor cells may contribute to an apoptosis resistant phenotype." (PMID 36776395, 2022). "Similarly, a high number of tumor-associated macrophages lead to an increased production of angiogenic factors such as VEGF, PDGF, IL-8, TNF-α und bFGF and an enhanced expression of angiogenesis promoting enzymes such as MMP-2, MMP-7, MMP-9 and MMP-12." (PMID 34821752, 2021). "In addition to MMP-2 and TIMP-2, MMP-7 is also relevant for tumor pathogenesis." (PMID 32751899, 2020). "Moreover, MUC16-MSLN interaction can also trigger tumor invasion through MMP-7 activation." (PMID 32612258, 2020). "In this study, we demonstrate that SREBP1 expression could not only increase the proliferation of tumor cells by modulating the lipid metabolic pathway, it may also activate the NF-κB pathway, elevate the expression of MMP7 to promote tumor invasion and metastasis." (PMID 31299935, 2019). "Similarly, MMP7 was ever screened out among novel plasma tumor markers, consisting of 11 genes." (PMID 29088749, 2017). "Moreover, we demonstrated that the utilisation of a combined panel of MMP-7 with both known tumor markers undoubtedly improved cancer detection in every stage, but especially in the early stages of the disease (0.8343 and 0.8324 vs 0.8635; respectively – I stage)." (PMID 28662671, 2017). "Thus, our data demonstrated that ARF may increase MMP7 levels to boost tumor microenvironments in human advanced PCa." (PMID 27356744, 2016). "The working hypothesis of this investigation was that perlecan and MMP-7 levels and localization are coordinately regulated in the tumor microenvironment, and a pathophysiologic relationship between these factors may predict the risk of invasion and metastases in a subset of PCa patients." (PMID 26862737, 2016).
tumor (continued). "MMP-7 and MMP-9, which belongs to a family of zinc-dependent endopeptidases, are collectively capable of degrading essentially all of the components of the extracellular matrix (ECM), and are considered to be associated with invasion and migration of tumor cell." (PMID 26909600, 2016). "Interestingly, MMP-7 is localized at the invasive protrusions of tumor cells." (PMID 25823818, 2015). "We demonstrated that treatment strategies containing metformin significantly reduced tumor growth and metastasis in nude mice, and that metformin caused an increase in AMPK and PTEN activity and suppression of mTOR/p70S6K/S6, as well as invasion/migration-associated genes, e.g., MMP7, DCN and FN1." (PMID 25909163, 2015). "Therefore, MMP-7 and TIMP-2 may be useful molecular markers for evaluating prognosis in CCRCC patients and MMP-7 may be a new target for the prevention of tumor development and improvement of survival rate." (PMID 23408109, 2013). "However, considering the previously shown localised presence of MMP-7 at the invasive front of tumours, immunohistochemical or in vitro studies might further elucidate this functional relationship." (PMID 16940985, 2006). "In cSCC, the most expressed MMPs by tumor cells and stromal cells are MMP-1, MMP-7, MMP-9, MMP-13, and MMP-14." (PMID 40868818, 2025). "IL-6 also promoted angiogenesis, tumor invasion, and metastasis through the regulation of hypoxia-inducible factor 1α (HIF-1α), matrix metalloproteinases (MMP2, MMP7, MMP9), and vascular endothelial growth factor (VEGF)." (PMID 40160826, 2025). "In HNC, CXCL11 promotes tumor angiogenesis and epithelial–mesenchymal transition (EMT), aiding in metastasis and immune evasion through JAK/AKT and MMP7 activation." (PMID 40606440, 2025). "MMP7 and MMP11 showed moderate cytoplasmic staining, while MMP14 exhibited stronger and more diffuse staining, suggesting its prominent role in tumor invasion and extracellular matrix remodeling." (PMID 40604111, 2025). "For the combined parameters, the highest increase in SE was noted in both subgroups for MMP-7+CA125 (92% for stage I EC and 96% for stage II EC), while SP was reduced in all combinations of MMPs with the tumor marker." (PMID 40332487, 2025). "SMAD4 participates in tumor metastasis and infiltration by transcriptionally regulating transforming growth factor beta (TGF-β) signaling pathway, such as MMP7 and N-cadherin, and was enriched in the PPI network we constructed." (PMID 41170449, 2025). "The binding of MSLN to MUC16 not only enhances the adhesion ability of tumor cells but also upregulates the expression of MMP7 through the PI3K/AKT signaling pathway, thereby strengthening the invasive capacity of these tumor cells." (PMID 41400642, 2025). "MMP7 and MMP11 were significantly upregulated in primary SKCM but showed reduced expression in metastatic samples, suggesting their involvement in early tumor invasion and progression." (PMID 40604111, 2025). "In the tumor region, DEGs included ECM-related genes such as MMP7, LCN2, chemokine CXCL5, and tumor markers CLDN4 and MUC4." (PMID 40303346, 2025). "Isoform structure analysis using GEPIA2 revealed functional diversity in MMP7, MMP11 and MMP14, highlighting their roles in ECM degradation and tumor progression." (PMID 40604111, 2025). "Similar to MMP7, MMP13 is a key enzyme in cancer progression, promoting tumor cell migration, metastasis, and angiogenesis by degrading the extracellular matrix and activating epithelial-mesenchymal transition (EMT), thereby enhancing tumor invasiveness." (PMID 40168262, 2025). "It is known that matrix metalloproteinases (MMPs), including MMP7, MMP9, and MMP12, are secreted by both tumor and stromal cells, and they function to regulate metastasis by degrading extracellular matrix." (PMID 40750784, 2025). "In this model, YAP1 upregulation suppressed CXCL16-driven CD4+/CD8+ TIL recruitment and increased MMP7 expression, resulting in elevated RCB scores and reduced tumor remission." (PMID 40731926, 2025).
tumor (continued). "Tumor-specific stem-like cells (tSTM, cluster 0) exhibited strong upregulation of OLFM4, LEFTY1, SOD3, LCN2, SLC12A2, and MMP7, consistent with proliferative, inflammatory, and invasive phenotypes." (PMID 41282138, 2025). "By connecting different polymer layers with a peptide chain sensitive to matrix metalloproteinase-7 (MMP-7), an enzyme overexpressed in most tumors, encapsulated MSCs can achieve selectively accumulation in tumor areas." (PMID 38392750, 2024). "MMP-10 can also upregulate the expression of MMP-7, MMP-9, and MMP-13, which are critical for tumor progression." (PMID 39247608, 2024). "For example, MMP7 and CXCL14, which play important roles in tumor cell invasion and inflammation, respectively, Xenium data clearly indicated that tumor cells were responsible for their expression." (PMID 39639005, 2024). "MMP-7 or matrilysin, involved in the degradation of ECM elastin, is produced by MM cells, secreted and activated extracellularly, and stimulates tumor growth and metastasizing." (PMID 39063046, 2024). "Expression levels of Jagged1, MKP-1, MMP7, Notch1, SSBP2, and ZMIZ1 in tumor tissues of LV-ZMIZ1-RNAi CAL-27 mice were decreased compared to the control group (P < 0.05)." (PMID 38866828, 2024). "To summarise, our study provides insights into the composition of immune cells within tumours in NSCLC and emphasises the presence of CD14+APOE+ cells and MMP7+ tumour cells in close proximity as significant factors in immune exclusion." (PMID 39187937, 2024). "MMP-10 can also upregulate the expression of MMP-7, MMP-9, and MMP-13, which are critical for tumour progression." (PMID 38911387, 2024). "In cancer cells, GOLM1 has the ability to be released into the cytoplasm and acts as a molecular chaperone to interact with various tumour‐related molecules such as EGFR, RTK, MMP2, MMP7 and B3‐H7, exerting a pro cancer effect." (PMID 39470578, 2024). "Our findings align with the transcriptomics study, as we detected the presence of MMP7+ tumour cells and CD14+APOE+ cells in the NSCLC tumour region." (PMID 39187937, 2024). "It has been found that matrix metalloproteinase-7 (MMP-7) disrupts and degrades the perlecan complex bound in the ECM, thereby facilitating circulating tumor cell production and distant metastasis in PCa." (PMID 38240702, 2024). "Expression of invasion and metastasis-related proteins MKP-1, MMP-7, and SSBP2 were also significantly increased in TSCC tumor tissues, consistent with a propensity of tumor cells to metastasize." (PMID 38866828, 2024). "Acetyl-CoA acetyltransferase 1 (ACAT1) has been shown to be downregulated in KIRC and overexpression of ACAT1 can inhibit the secretion of MMP7 in KIRC cells, thereby inhibiting tumor invasion." (PMID 37627013, 2023). "Tumor cells co-expressing mesothelial and CA125 can increase the synthesis of MMP-7 and promote tumor metastasis." (PMID 36705352, 2023). "Using the Kruskal–Walls test to compare data, we found that overexpression of VEGFA, CTNNB1, MMP7, and CD44 genes promoted primary tumor and cancer metastasis in CRC tissues." (PMID 36672201, 2023). "PLAGL2 combines with the Wnt6 promoter and activates the β-catenin-dependent Wnt signaling pathway, thereby stimulating various downstream target genes (such as MMP7, CCND1) and promoting tumor development." (PMID 38003292, 2023). "To demonstrate that the transcriptomic profiles during AOIs selection reflected the histological definition of tumor invasive margin, we evaluated the mRNA levels of MMP1, MMP7, and MMP11 in tumor invasive margin, tumor center, and adjacent normal areas." (PMID 37964075, 2023). "EGCG decreased AsPC-1 xenograft tumor volume, angiogenesis, and metastasis together with downregulation of MMP2, MMP7, MMP9, and MMP12." (PMID 36677584, 2023).
tumor (continued). "To explore the source of MMP7 and MMP12 in UBC, we analysed UBC patient tumour samples that underwent single-cell sequencing and identified epithelial cells as the source of MMP7 and macrophages as the source of MMP12 mRNA transcripts." (PMID 37391708, 2023). "Our computer-based analysis revealed that the messenger (m)RNA levels of VEGFA, CTNNB1, MMP7, and CD44 oncogenic signatures were upregulated in tumor samples compared to normal samples of patients with CRC tissues, with significant p values (<0.05)." (PMID 36672201, 2023). "The DSP analysis unveiled a decrease in molecules that promote tumour growth, such as CHIL3, EpCAM, MMP7 and several pathways, including CAM and PI3K‐AKT signalling pathway." (PMID 38131168, 2023). "WNT1 not only accelerates the proliferation of tumors by upregulating c-Myc, but also promotes the tumor malignant proliferation and angiogenesis by inducing the expression of target genes such as Cyclin D1, VEGF-A, and matrix metalloproteinase 7 (MMP7)." (PMID 37486552, 2023). "Previous studies demonstrated that STAT3 can directly or indirectly interact with the promoters of cyclin D1, Twist, MMP2, MMP7, MMP9, VEGF, upregulate their expression and regulate cell proliferation, tumor metastasis and angiogenesis." (PMID 36295083, 2022). "The protein family of matrix metalloproteinases can degrade extracellular matrix components, whose well-known role is modulating tumor metastases, such as MMP2, MMP9, MMP7, MMP13, and MMP14." (PMID 35690612, 2022). "It is involved in tumor invasion and progression and can activate other MMPs, such as MMP-1, MMP-7, MMP-8, MMP-9 and MMP-13, which have an established role in OSCC." (PMID 36547091, 2022). "The primary role of MMP7 is to facilitate degradation of the extracellular matrix (ECM), which constitutes the major components of the tumor microenvironment (TME) together with blood vessels, signaling molecules, immune cells, and fibroblasts." (PMID 35785154, 2022). "Further, the authors revealed that miR-145-5-p controlled tumor cell migration and invasion by suppressing the expression of Matrix Metallopeptidase 2 (MMP2), N-cadherin, Focal adhesion kinase and Matrix Metallopeptidase 7 (MMP7)." (PMID 35269744, 2022). "BB94 is a potent extracellular broad-spectrum MMP inhibitor that inhibits MMP-1, MMP-2, MMP-3, MMP-7, and MMP-9 and distant tumor metastases." (PMID 35440570, 2022). "The intact form of this protein was found increased in tumor prostate tissue, but in sera from PCa patients raised levels of HSPG2-derived fragments resulting from matrix metalloproteinase 7 (MMP7) degradation were observed." (PMID 35454907, 2022). "Elevated levels of matrix metalloproteinase 7 (MMP-7), an enzyme with key roles in extracellular matrix remodelling during tissue repair and tumour progression, have been found in the serum of patients with CCA." (PMID 34660269, 2021). "Based on the TCGA and GTEx data, we found that MMP1, MMP3, MMP7, MMP9, MMP12, MMP13 all increased in the tumor as compared with the normal esophageal tissues." (PMID 34559117, 2021). "MMP1, MMP3, MMP7, MMP12, and MMP13 belong to the matrix metalloproteinase family, and MMPs were able to participate in the tumor metastasis process by degrading the ECM." (PMID 34381520, 2021). "Western blot assay demonstrated that the downregulation of ALKBH5 reduced the expression of the tumor metastasis-related proteins matrix metallopeptidase 2 (MMP2), MMP7, and MMP9 in UM cells." (PMID 33428593, 2021). "MMP2, MMP7, and MMP9 are members of the MMP family and are mainly involved in tumour invasion and metastasis." (PMID 33995637, 2021). "MMP7 overexpression is related to the enhanced invasive and metastatic capability of MDR tumor cells." (PMID 34589084, 2021). "It is known that MMP-7 and MMP-9 are also strong promoters of cancer progression and metastasis of malignant tumor cells." (PMID 33435313, 2021).